TLR9 (toll like receptor 9)
Diseases named in the same sentence as TLR9 in open-access papers (continued):
Sharing a sentence is not in itself a finding about the gene and the disease.
brain cancer (4 papers, 2010 to 2022). A primary or metastatic malignant neoplasm affecting the brain. "In conclusion, hypoxia regulates the invasion of brain cancer cells in vitro in a TLR9-dependent manner, which is considered to be associated with a complex expression pattern of TLR9-regulated mediators and inhibitors of invasion." (PMID 24959259, 2014). "This novel observation may have therapeutic implications in brain cancers, particularly for those tumors that exhibit high hypoxia-associated TLR9 expression at diagnosis." (PMID 24959259, 2014). "In addition, our studies further suggest that TLR9 expression is significantly associated with the invasive machinery in brain cancer cells and may mediate hypoxia-induced invasion in brain cancer." (PMID 24959259, 2014). "It has been demonstrated that neighboring oxygen levels have an important effect on TLR9 expression and function in human brain cancer cells in vitro." (PMID 36611945, 2022). "TLR9 mediates the invasion-induced hypoxia of brain cancer cells by the activation of matrix metalloproteinases (2, 9, and 13) in brain tissues." (PMID 36611945, 2022). "The present study demonstrated that hypoxia upregulates and downregulates TLR9 expression in human brain cancer cells in vitro, in a cell-specific manner." (PMID 24959259, 2014). "In conclusion, these results suggest that the downregulation of TLR9 expression inhibits the hypoxia-induced invasion of brain cancer cells in vitro." (PMID 24959259, 2014). "Overall, these results suggest that the downregulation of TLR9 in brain cancer cells results in decreased basal and DNA ligand-induced invasion in normoxia, in a cell-specific manner." (PMID 24959259, 2014). "In conclusion, hypoxia regulates TLR9 expression in brain cancer cells in vitro and TLR9 also mediates the hypoxia-induced invasion of these cells." (PMID 24959259, 2014). "The present study demonstrated that the surrounding oxygen level has an important effect on TLR9 expression and function in human brain cancer cells in vitro." (PMID 24959259, 2014). "TLR9 is widely expressed in a number of tumors, including brain cancer; however, little is known regarding its regulation and involvement in cancer pathophysiology." (PMID 24959259, 2014). "In addition, these studies further suggest a powerful link between TLR9 expression and the invasive machinery in brain cancer cells which can promote brain cancer hypoxia-induced invasion by the activation of MMP 2, 9, and 13 in brain tissues." (PMID 36611945, 2022). "Although widely expressed in various tumors, including brain cancer, the contribution of TLR9 to cancer pathophysiology remains unclear and the regulation of TLR9 expression in cancer is also poorly understood." (PMID 24959259, 2014). "Although this phenomenon requires further study in vivo, the results of the current study suggest that the suppression of TLR9 expression and activity may present a novel molecular target in brain cancer." (PMID 24959259, 2014). "The reciprocal interaction between TLRs and HIF-1α suggests that hypoxia-induced TLR9 expression may also be HIF-1α-regulated in brain cancer cells." (PMID 24959259, 2014). "The less invasive phenotype of TLR9 siRNA cells in normoxia and hypoxia suggests that TLR9 may mediate the high levels of brain cancer cell invasion into the healthy brain tissue in clinical tumors, through regulation MMP expression and activity." (PMID 24959259, 2014). "Overall, these observations suggest that TLR9 expression may contribute to the increased invasion of brain cancer cells under hypoxic tissue conditions." (PMID 24959259, 2014). "Thus, TLR9 promotes hypoxia-induced brain cancer cell invasion." (PMID 36611945, 2022). "These proteases may be TLR9-regulated in brain cancer cells." (PMID 36611945, 2022).
brain cancer (continued). "Notably, hypoxia has also been shown to activate MMP-2, -9 and -13 in brain tissues; however, the current study is the first to demonstrate that these proteases may be TLR9-regulated in brain cancer cells." (PMID 24959259, 2014). "Due to the previously demonstrated associations between hypoxic tissue conditions and the upregulation of TLR2 and 6 in various normal tissues, we hypothesized that hypoxic tissue conditions may activate TLR9-expression and the TLR9-mediated invasive pathway in brain cancer cells." (PMID 24959259, 2014). "Similar effects on TLR9 mRNA expression by chloroquine were also detected in the D54MG and U373MG brain cancer cell lines." (PMID 24273604, 2013).
cardiomyopathy (4 papers, 2015 to 2023). A disease of the heart muscle or myocardium proper. "Inhibition of TLR9 also attenuated the development of cardiomyopathy." (PMID 38136887, 2023). "While systemic administration of TLR9 agonist has been shown to attenuate myocardial hypertrophy and dysfunction in both isoproterenol and pressure overload-induced cardiomyopathy, we found worsening of diastolic function in a model of diastolic HF with no attenuating effects on systolic function." (PMID 26461521, 2015). "Thus, while systemic administration of a TLR9 agonist inhibited cardiac hypertrophy and dysfunction in isoproterenol and pressure overload-induced cardiomyopathy, TLR9 activation restricted to the cardiomyocyte leads to aggravated HF, this noteworthy also in pressure overload induced cardiomyopathy." (PMID 26461521, 2015). "In the absence of either TLR3 or TLR9, the intensity of echocardiogram (Echo)-Doppler dysfunction during development of cardiomyopathy was substantially reduced in the K.O. mice." (PMID 30364002, 2018).
chronic hepatitis B (4 papers, 2011 to 2022). "Compared with healthy individuals, patients with chronic hepatitis B had decreased serum TLR9 protein expression under HBV stimulation, but the TLR9 protein expression increased after a certain period of treatment." (PMID 36596032, 2022). "To corroborate our in vitro data we isolated PBMC from ten European chronic hepatitis B patients and ten healthy blood donors and analyzed TLR9 mRNA and protein levels." (PMID 22046272, 2011). "TLR9 gene binds with H3K9Ac in the serum PBMCs of healthy individuals, HBV-infected patients, and patients with chronic hepatitis B treated with entecavir and thymosin a1." (PMID 36596032, 2022). "TLR9 mRNA expression was found to be suppressed in HBV chronic infection in the Tupaia model, which is consistent with a previous report showing reduced TLR9 expression in peripheral CD14+ monocytes of chronic hepatitis B patients." (PMID 31842286, 2019).
dysplasia (4 papers, 2019 to 2026). A usually neoplastic transformation of the cell, associated with altered architectural tissue patterns. "For TLR9 expression, high levels were found in 35% of severe dysplasia cases, while very high levels were observed in 17.5% of cases." (PMID 41374999, 2025).
experimental autoimmune encephalomyelitis (4 papers, 2016 to 2023). An autoimmune demyelinating disease of the central nervous system that is produced experimentally in animals by the injection of homogenized brain or spinal cord in Freund's adjuvant. "Here, we show that bone marrow cells transiently stimulated in vivo or in vitro through the Toll-like receptor 9 generate proB cells (CpG-proBs) that interrupt experimental autoimmune encephalomyelitis (EAE) when transferred at the onset of clinical symptoms." (PMID 27396388, 2016).
glomerular diseases (4 papers, 2014 to 2024). "Thus, de novo expressed TLR9 may utilize endogenous mtDNA as the ligand to facilitate podocyte apoptosis, a novel mechanism underlying podocyte injury in glomerular diseases." (PMID 26934958, 2016). "It appears that TLR9 is turned on in podocytes of a quite broad spectrum of glomerular disease, although this takes place in only a portion of the patients in each disease." (PMID 26934958, 2016). "TLR9 is de novo expressed in podocytes of some patients with glomerular diseases, but its role in podocyte injury remains undetermined." (PMID 26934958, 2016). "It would be interesting to understand how TLR9 is upregulated in podocytes of only part of the patients with lupus nephropathy or several other glomerular diseases." (PMID 26934958, 2016). "Inhibition of TLR9 activity may help halt the progression of glomerular diseases in the patients that have de novo TLR9 expression in the podocytes." (PMID 26934958, 2016). "Since TLR9 activates p38 MAPK and NFkB that are known to mediate podocyte apoptosis, we hypothesized that TLR9 induces podocyte apoptosis in glomerular diseases." (PMID 26934958, 2016).
ileitis (4 papers, 2014 to 2020). "Apart from TLR2, TLR4, and TLR11, TLR9 also contributes to the ileitis immunopathology after oral infection with Toxoplasma." (PMID 33178630, 2020). "Also, TLR9 might have an important role in the immunity against T. gondii, since TLR9-deficient mice, infected with the parasite, were comparatively resistant to the ileitis, revealing a decreased Th1 immune response." (PMID 26254559, 2015). "In the present study we performed a comprehensive survey of quantitative and qualitative changes in the intestinal microbiota composition of TLR-9-/- and WT control mice following ileitis induction." (PMID 24932221, 2014). "However, contradictory reports indicate that although wild-type and Tlr9−/− mice exhibit a comparable degree of ileitis upon oral Toxoplasma infection, the latter develops a higher parasite burden and higher IFNγ and NO levels." (PMID 33178630, 2020). "We here show that TLR-9 is not required for the development of T. gondii induced ileitis but mediates distinct inflammatory changes in intestinal and extra-intestinal compartments including the brain." (PMID 24932221, 2014). "Seven days following peroral infection (p.i.)with 100 cysts of T. gondii ME49 strain, TLR-9-/- and wildtype (WT) mice suffered from comparable ileitis, whereas ileal parasitic loads as well as IFN-γ and nitric oxide levels were higher in TLR-9-/- compared to WT mice." (PMID 24932221, 2014). "Interestingly, FOXP3+ regulatory T cell (Treg) numbers increased in WT, but not TLR-9-/- mice upon ileitis induction (p < 0.001)." (PMID 24932221, 2014).
latent infection (4 papers, 2010 to 2022). "In early latent infection, EBV can be induced to enter the lytic cycle by a variety of causes including B-cell receptor stimulation, Toll-like receptor-9 activation, hypoxia, and growth factors." (PMID 26468873, 2015). "Our results suggested an association between TLR9 genetic polymorphisms and the development of PTB from latent infection in Chinese population." (PMID 24176007, 2013). "For example, the increase of lytic and latent viral loads observed in spleen, but not in lungs of TLR9−/− mice as compared to control groups suggest that TLR9 is important in organ-specific immunity against MHV-68 during both lytic and latent infection." (PMID 21060793, 2010).
mantle cell lymphoma (4 papers, 2014 to 2022). Mantle cell lymphoma is a rare form of malignant non-Hodgkin lymphoma affecting B lymphocytes in the lymph nodes in a region called the ``mantle zone''. "A study showed that treatment with CpG, a TLR9 agonist, promoted MHC-II presentation of IG-derived neoantigens of mantle cell lymphoma cells." (PMID 31640780, 2019). "Follicular lymphoma or mantle cell lymphoma also showed an increased expression of CD80 and/or CD86 in response to TLR9 agonist." (PMID 29805758, 2018). "In mantle cell lymphoma (MCL), TLR1, TLR4, TLR7, TLR9 and TLR10 exhibit significant mRNA levels, whereas TLR2, TLR3, TLR5 and TLR8 are negative." (PMID 25112836, 2014).
mucositis (4 papers, 2012 to 2022). Mucositis is inflammation and damage of the mucous membranes lining the mouth and other parts of the gastrointestinal (GI) tract. "The protective role of MyD88 and TLR2 and TLR9 in irinotecan-induced mucositis was associated with a pronounced reduction of the local inflammatory reaction, as detected by the measurement of myeloperoxidase activity and COX–2 and IL–1β production." (PMID 26440613, 2015). "In addition, similar to the TLR2-/- and TLR9-/- mice, the mice with a genetic deletion of MyD88 were markedly protected from the development of mucositis, as indicated by a reduced production of inflammatory markers and intestinal damage." (PMID 26440613, 2015). "Therefore, the current evidence demonstrates that activated TLR9 plays a proinflammatory role in mucositis, suggesting that the inhibition of TLR9 may also be a potential therapeutic target for RIOM/CIOM." (PMID 35719331, 2022). "Finally, we recently demonstrated that systemic administration of the synthetic TLR9 agonist protects against intestinal injury and mucositis in radiation-induced gastrointestinal syndrome, without conferring any radioprotection to abdominal tumors." (PMID 22666458, 2012).
myasthenia gravis (4 papers, 2017 to 2025). Myasthenia gravis (MG) is a rare, clinically heterogeneous, autoimmune disorder of the neuromuscular junction characterized by fatigable weakness of voluntary muscles. "Originally designed as a therapy for myasthenia gravis due to its effects on acetylcholinesterase transcripts, BL-7040 was shown to be an activator of TLR9 signaling to increase levels of indoleamine and IFNα." (PMID 29515999, 2018). "We report here the sequence and functional characterization of a recombinantly expressed autoantibody (mAb 131) previously isolated from a myasthenia gravis patient by immortalization of thymic B cells using Epstein-Barr virus and TLR9 activation." (PMID 29089519, 2017). "Unlike autoimmune myocarditis, myasthenia gravis (MG) and its models require activation of TLR3 and TLR9, but not TLR2 and no NOD or NLR involvement has been reported for either patients or in animal models (although this may be because no one has yet looked for it)." (PMID 32629865, 2020).
pneumococcal pneumonia (4 papers, 2012 to 2019). A febrile disease caused by STREPTOCOCCUS PNEUMONIAE. "Previous studies have implicated TLR9 and MyD88 as important players in protective immunity in pneumococcal pneumonia." (PMID 22721450, 2012). "In vivo, especially TLR9 was reported to be important for host defense during pneumococcal pneumonia, as reflected by increased bacterial growth and lethality in tlr9−/− mice; myd88−/− mice displayed a similar hypersusceptible phenotype." (PMID 23483993, 2013). "In these studies, only TLR9 was identified as a nonredundant receptor in a murine pneumococcal pneumonia model." (PMID 26956584, 2016). "The amelioration of inflammatory responses in the lung during pneumococcal pneumonia by ibrutinib may also result from inhibition of other Btk-dependent receptors that regulated S. pneumoniae-induced lung inflammation, including TLR4, TLR9, TREM-1 and NLRP3." (PMID 30646846, 2019).
primary Sjögren’s syndrome (4 papers, 2011 to 2023). "Activation of the TLR9 signaling pathway has been observed in patients with primary Sjögren’s syndrome based on single cell phosphorylation profiling." (PMID 37264476, 2023). "It is plausible to assume that extracellular HMGB1 acts as an inflammatory cytokine through TLR9 signaling on B cells in this mouse model of Sjӧgren’s syndrome." (PMID 28837629, 2017). "Salivary gland biopsy sections from primary SjS patients and Sicca syndrome controls were tested for markers of TLR9 activity and cholinergic signaling." (PMID 22174879, 2011). "The purpose of our study was to understand if Toll-like receptor 9 (TLR9) activation could contribute to the control of inflammation in Sjogren's syndrome." (PMID 22174879, 2011).
Respiratory tract infection (4 papers, 2012 to 2022). An infection of the upper or lower respiratory tract. "Future studies are warranted to investigate the role of MyD88 and TLR9 in asplenic animals during respiratory tract infection caused by the pneumococcus." (PMID 22721450, 2012). "Although SARS-CoV-2 is not predicted to directly activate DNA sensors, damage during respiratory tract infection can lead to production of oxidized mitochondrial DNA (ox-mtDNA), which is known to be a potent ligand for TLR9." (PMID 36099266, 2022). "Regarding the stimulation of TLR9, respiratory tract infection may trigger TLR9 activity." (PMID 33420306, 2021). "Several MyD88 dependent TLRs are known to be important for the innate immune response to respiratory tract infection with K. pneumoniae, particularly TLR4 and TLR9, and during late stage infection or in the presence of high bacterial numbers, TLR2." (PMID 25254554, 2014).
squamous cell carcinoma (4 papers, 2014 to 2024). A carcinoma arising from squamous epithelial cells. "We demonstrated an increased TLR9 expression in esophageal squamous dysplasia and in squamous cell carcinoma, suggesting a possible role for TLR9 in esophageal carcinogenesis." (PMID 24847326, 2014). "Summarizing the Results section, significant differences were observed in the expression of various TLRs (TLR-2, TLR-3, TLR-4, TLR-7, TLR-8, and TLR-9) on selected T and B cell subpopulations between the patients with squamous cell carcinoma (SCC) and the healthy controls." (PMID 39124797, 2024). "The TLR-9 gene was found to have lower expression inCIN 1 than in CIN 2/3 and to have the highest expression in squamous cell carcinoma samples." (PMID 37886144, 2023).
type 2 diabetes (4 papers, 2013 to 2023). "TLR9 message and protein expression levels which are higher in diabetic wounds compared to control wounds have been linked to impaired wound healing in type 2 diabetes mellitus (T2DM) cases via the induction of pro-inflammatory S100A8 and IL-8." (PMID 33519463, 2020). "Increased TLR4 expression leads to type 2 diabetes by reducing insulin secretion by β-cells and together with TLR2 and TLR9 contribute to the development of neurological disorders like schizophrenia and autism." (PMID 27307950, 2016).
vitiligo (4 papers, 2020 to 2025). Generalized well circumscribed patches of leukoderma that are generally distributed over symmetric body locations and is due to autoimmune destruction of melanocytes. "In line with the important role of IFNα in disease pathogenesis, hydroxychoroquine, a TLR7 and TLR9 inhibitor downregulating IFNα production by pDCs, was shown to induce repigmentation of vitiligo lesions in a clinical case reports." (PMID 33936032, 2021). "As described in the section on TLR7, increased expression of TLR7 and TLR9 are observed in melanocytes obtained from vitiligo lesions." (PMID 33371432, 2020). "Interestingly, we showed increased expression of TLR7 and TLR9 in vitiligo melanocytes in a recent study, emphasizing a role of TLR7 and TLR9 in hypopigmentation." (PMID 34614305, 2022). "Melanocytes collected from vitiligo lesions show an increase of TLR7 and TLR9 expression along with an increase of the apoptosis level and a decrease of the melanin synthetic ability." (PMID 33371432, 2020).